ESR1 (estrogen receptor 1)
Diseases named in the same sentence as ESR1 in open-access papers (continued):
Sharing a sentence is not in itself a finding about the gene and the disease.
Obesity (continued). "We then tested whether saturated free fatty acids (FFAs), whose levels are abundant in HFDs and are commonly elevated in obesity, regulates DNA methylation levels at the Esr1 promoter." (PMID 40666843, 2025). "Moreover, it appeared that ESR1 contributes to type 2 diabetes and CVD risk via pleiotropic effects, leading to insulin resistance, a poor lipid profile, and obesity." (PMID 35990823, 2022). "However, the correlation between ESR1 and obesity was less significant (Pearson r = 0.225), compared to the association between YAP and obesity (Pearson r = 0.476)." (PMID 35182054, 2022). "In order to determine whether epigenetic modifications play a role in regulating obesity-related changes in ESR1 and ESR2 mRNA levels in adipose tissues, we investigated the methylation status of the regulatory regions of these two genes." (PMID 35682668, 2022). "ESR1 shared a negative correlation with obesity in adipose tissues and a positive association with mitochondrial metabolism-related genes and metabolic health markers." (PMID 35267929, 2022). "One may wonder about the primary phenomenon: whether excess adiposity causes a decrease in ESR1 and ESR2 expression or whether their decreased levels predispose humans to obesity." (PMID 35682668, 2022). "Consistently, female mice with Esr1 deletion in the brain develop obesity." (PMID 33826123, 2022). "Esr1-knockout mice display decreased longitudinal bone growth, increased body weight and obesity." (PMID 26911590, 2016). "The associations of ESR1 variants with obesity-related traits are supported by the association of PvuII polymorphism of ESR1 with total fat mass in young Chinese men and by the manifestation of obesity and insulin resistance in ER alpha (ESR1)−/− mice." (PMID 23300848, 2012). "ESR-1, LPL, and APO E genetic polymorphic variants could represent predictive genetic risk markers for obesity-related metabolic disorders in young healthy subjects." (PMID 19804633, 2009). "ESR1 is also expressed by thymocytes and B- and T-cells and Esr1 knockout mice exhibit compromised thymic and B-cell development, insulin resistance, impaired glucose tolerance and obesity." (PMID 18636124, 2008). "Although no ESR1 SNP displayed allelic association with obesity, we cannot completely exclude an impact of ESR1 alleles on female obesity since genotyped SNPs failed to capture a few common haplotypes in the region of the ESR1gene." (PMID 18053221, 2007). "We also had nominal significance with a SNP in LD with the ESR1 Xba1 SNP, and multiple other SNPs in well-replicated obesity genes, suggesting that the Affymetrix 100K GeneChip provides a valid tool for uncovering candidate gene associations with adiposity-related traits." (PMID 17903300, 2007). "Esr1 signalling in the VMHvl was previously demonstrated to influence food intake, energy expenditure and glucose tolerance and VMHvl-restricted knockdown of Esr1 resulted in increased food intake, decreased physical activity and thermogenesis, reduced glucose tolerance and obesity in female rats." (PMID 36184065, 2022). "We selected miRNAs for this analysis that met three primary criteria: (i) a predicted in silico interaction with ESR1 or ESR2 mRNA, (ii) a suggested role in the regulation of ESR1 or ESR2 expression in vivo, and (iii) an altered expression in adipose tissue in the course of obesity or weight loss." (PMID 35682668, 2022). "Interestingly, in the obese patients after weight loss, the ESR1/ESR2 mRNA ratio in SAT and VAT remained elevated, suggesting that obesity may leave a permanent mark on adipose tissue function." (PMID 35682668, 2022). "Given the role of epigenetic mechanisms in regulating the expression of genes encoding ERs in estrogen-dependent tumors, we investigated whether DNA methylation and miRNA interference participated in the observed obesity-induced decrease in the ESR1 and ESR2 mRNA levels in adipose tissue." (PMID 35682668, 2022).
Obesity (continued). "Similarly, genes ESR1, SERPINE1 and VEGFA are shared across diabetes (EGFR, GSTP1, SERPINE1, ESR1, VEGFA and EGF) and obesity (CCND1, SERPINE1, ESR1 and VEGFA), which is in line with previous reports that obesity is a risk factor of diabetes." (PMID 31835887, 2019). "However, the significance was lost when analysis was adjusted for circulating E2, suggesting that hyperestrogenemia following obesity and not obesity itself, causes lower ESR1 expression." (PMID 30181488, 2018). "Additionally, oestrogen sensitivity (indicated by ESR1 expression) in HG men is influenced by available oestrogen and those with obesity-induced hyperestrogenemia have reduced E2 sensitivity relative to HG men with lower E2, resulting in a variable response to T therapy." (PMID 30181488, 2018). "Additionally, select gut microbiome residents in ESR1 KO males, such as Lachnospiraceae and Christensenellaceae, might contribute to previously identified phenotypes, especially obesity, in these mutant mice." (PMID 26971397, 2016). "Our finding that ESR1 mRNA levels in adipose tissue are inversely correlated with rate of basal lipolysis might suggest that low adipose tissue ESR1 levels, as observed in obesity, increases basal lipolysis." (PMID 18053221, 2007). "No ESR1 SNP displayed allelic association with obesity or lipolysis." (PMID 18053221, 2007). "ESR1 gene alleles are unlikely to be a major cause of obesity in women." (PMID 18053221, 2007). "However, whether ESR1 protects against obesity or is upregulated as a result of low BMI remains to be established." (PMID 18053221, 2007). "ESR1 can also regulate the expression of MMAA, an obesity-metabolism differential gene, to prevent HCC, as shown in a study in females." (PMID 41048345, 2025). "We suggest that elevated aromatase content in SAT, together with altered ESR1/ESR2 balance, in men with obesity contributes to the development of insulin resistance and T2D." (PMID 39833659, 2025). "In this study, we aimed to investigate the role of ARO, ESR1, and ESR2 in SAT from men with obesity and T2D." (PMID 39833659, 2025). "We have previously shown in female mice that muscle-specific ERα knockout (MERKO) reduces oxidative metabolism and insulin sensitivity, and this mouse model recapitulated the obesity-insulin resistance phenotype of whole-body Esr1−/− animals." (PMID 40328250, 2025). "In this study, we investigated the expression of ARO, ESR1, and ESR2 in SAT and VAT from men with varying degrees of obesity and T2D, as well as the effects of the sex steroids E2 and testosterone on adipocyte glucose uptake." (PMID 39833659, 2025). "Four differentially expressed genes, including ESR1, GCDH, FAHD2A, and DCXR, were found to overlap between HCC and obesity." (PMID 38977823, 2024). "In the present study, we have identified four differentially expressed genes shared between obesity and HCC, namely ESR1, GCDH, FAHD2A, and DCXR." (PMID 38977823, 2024). "Clarifying the obesity-differential genes in HCC patients and specifying their relationship with ESR1 are the key factors to illuminating how obese female patients benefit from HCC oncogenesis." (PMID 35795061, 2022). "However, these authors were unable to conclude whether reduced ESR1 expression was a cause or a consequence of obesity and whether differences in circulating E2 (not assessed in this study) played a role." (PMID 30181488, 2018). "This study explored alterations in ARO, ESR1, and ESR2 in men with obesity or T2D." (PMID 39833659, 2025). "The integration of metabolomics and network pharmacology has identified six hub targets, namely AKT1, EGFR, ESR1, STAT3, IGF1, and MAPK1, that may be critical for the effects of EGCG on obesity-related precocious puberty." (PMID 40807299, 2025).
Obesity (continued). "Our study demonstrates that enhanced DNA methylation at the Esr1 promoter by HFD plays an important role in mediating exaggerated adipose chemotaxis and inflammation, which may contribute to obesity-induced insulin resistance and type 2 diabetes." (PMID 40666843, 2025). "Four differentially expressed genes (ESR1, GCDH, FAHD2A, DCXR) were common in obesity and HCC." (PMID 38977823, 2024). "EGCG may contribute to preventing obesity-related precocious puberty through targets such as AKT1, EGFR, ESR1, STAT3, IGF1, and MAPK1 and multiple signaling pathways, including the estrogen, PI3K-Akt, MAPK, and Jak-STAT pathways." (PMID 37334310, 2023). "The integrated metabolomics and network pharmacology indicated that AKT1, EGFR, ESR1, STAT3, IGF1, and MAPK1 may be key targets for EGCG in preventing obesity-related precocious puberty." (PMID 37334310, 2023). "In summary, EGCG may serve a role in preventing obesity-related precocious puberty through targets such as AKT1, EGFR, ESR1, STAT3, IGF1, and MAPK1 that acted on multiple signaling pathways, including the estrogen, PI3K-Akt, MAPK, and Jak-STAT pathways." (PMID 37334310, 2023). "According to the results of integrated metabolomics and network pharmacology, 6 hub targets, including AKT1, EGFR, ESR1, STAT3, IGF1, and MAPK1, may play significant roles in the effects of EGCG on obesity-related precocious puberty." (PMID 37334310, 2023). "The present results denoted that the synergic effects of SNPs of rs712221 on the ESR1 gene and rs2016520 on the PPARD gene might play a substantial role in obesity development via impairing dietary metabolism, although much still remains to be explored." (PMID 36297109, 2022). "This study elucidates that obesity might be a protective factor for female HCC patients, as they originally highly expressed ESR1, which could upregulate MMAA to suppress tumor growth and participate in metabolic reprogramming." (PMID 35795061, 2022). "The obesity-related changes in ESR1 and ESR2 expression in adipose tissues did not correlate with the methylation status of the regulatory regions in these two genes." (PMID 35682668, 2022). "Thus, perhaps at some threshold level of increasing obesity, tumor growth could be fueled by heightened inflammatory processes, rather than estrogen exposure, thus leading to decreased ESR1 expression and lower likelihood of developing the associated intrinsic subtypes." (PMID 25884832, 2015). "Common ESR1 gene alleles are unlikely to contribute to obesity in women, whereas a minor importance of ESR2 on severe obesity cannot be excluded." (PMID 18053221, 2007). "Furthermore, our cohort of men was too small to exclude a male-specific impact of ESR1 and ESR2 on obesity." (PMID 18053221, 2007). "Neither ESR1 nor ESR2 protein levels were affected by obesity status." (PMID 39833659, 2025). "Men with obesity had lower levels of ESR1 and ESR1:ESR2 ratio, but not ESR2." (PMID 39833659, 2025). "We assessed whether there was an association between the gene expression of ARO, ESR1, and ESR2 in the combined cohorts 1 and 2, which included men with or without obesity or T2D." (PMID 39833659, 2025). "Additionally, 21 gene loci were differentially methylated in patients with obesity with and without ESR1-positivity, which were reportedly involved in the immune response, cell growth, and DNA repair." (PMID 37512149, 2023). "Interestingly, in contrast to ESR1 expression in SAT, obesity did not seem to induce significant changes in ESR1 expression in VAT." (PMID 35682668, 2022). "For example, a deficiency of the G-protein coupled estrogen receptor (Gper) or Esr1 in male mice induces insulin resistance and obesity, however it was not established whether an increase in Gper or Esr1 signaling would have the opposite effect." (PMID 35135593, 2022). "Subcutaneous adipose tissue (SAT) from men with or without obesity or T2D was analyzed for ARO, ESR1, and ESR2 gene and protein expression." (PMID 39833659, 2025).
Obesity (continued). "We also show that ESR1 and ESR1:ESR2 ratio, but not ESR2, gene expression levels in SAT are decreased in men with obesity." (PMID 39833659, 2025). "Gene and protein expression of ARO, ESR1, and ESR2 in SAT from participants with or without obesity (matched for age) or T2D (matched for age and BMI) was first assessed." (PMID 39833659, 2025). "However, in the absence of hepatic ESR1, TRF mitigated obesity in these mice, especially in fat mass." (PMID 40625849, 2025). "The core targets between estrogen and obesity are proto-oncogene, non-receptor tyrosine kinase (SRC), estrogen receptor 1 (ESR1), prostaglandin-endoperoxide synthase 2 (PTGS2), nuclear receptor subfamily 3 group C member 1 (NR3C1) and cytochrome P450 family 19 subfamily A member 1 (CYP19A1)." (PMID 39575382, 2024).
osteoporosis (267 papers, 2005 to 2026). A condition of reduced bone mass, with decreased cortical thickness and a decrease in the number and size of the trabeculae of cancellous bone (but normal chemical composition), resulting in increased fracture incidence. "The decline in estrogen levels, particularly in postmenopausal women, is a major risk factor for osteoporosis, and alterations in ESR1 expression or function can exacerbate this effect." (PMID 40421218, 2025). "For example, a study using Taiwan Biobank data found that individuals carrying the ESR1 rs2982573 genotype who consumed more than three cups of coffee per week had a lower risk of osteoporosis." (PMID 41373951, 2025). "Some single nucleotide polymorphisms (SNPs) within osteoporosis candidate genes, such as ESR1 and MHC, seem to have an influence on the age of natural menopause." (PMID 36982891, 2023). "The purpose of this study was to evaluate the effect of estrogen receptor 1 (ESR1) polymorphisms on the development of medication-related osteonecrosis of the jaws (MRONJ) in women with osteoporosis." (PMID 37415765, 2023). "Numerous osteoporosis susceptibility loci, including ESR1, LRP4, DAAM2, WNT 16, and SOX 6, have been found and investigated using multiomics techniques based on systems genetics and genomics." (PMID 35496311, 2022). "The aim of the study was to assess the effect of ESR1 gene polymorphisms on the increased risk of osteoporosis in women with hyperandrogenism." (PMID 36385124, 2022). "It is known that numerous polymorphisms of the ESR1 gene are associated with an increased risk of osteoporosis in postmenopausal women." (PMID 36385124, 2022). "Numerous studies have investigated sequence variants of the ESR1 gene in post-menopausal women groups with osteopenia and osteoporosis." (PMID 31450614, 2019). "ESR1, which encodes for the oestrogen receptor, has long been considered a candidate gene for osteoporosis, based on earlier linkage studies and oestrogens’ prominent physiological role in bone remodelling." (PMID 27533615, 2016). "ESR1 can regulate bone metabolism through genome-wide association studies (GWAS) and it inhibits osteoporosis as an estrogen receptor." (PMID 23731710, 2013). "The expressions of IL17RC, COL1A1, and ESR1 in bone marrow mesenchymal cell are expected to be used in developing biomarkers for detecting osteoporosis and for screening osteoporosis risk groups." (PMID 23731710, 2013). "Alleles associated with slower heart rate (rs365990, MYH6), decreased risk of osteoporosis and short body height (rs2982570, ESR1), decreased risk of schizophrenia (rs1339227, RIMS1-KCNQ5) and decreased risk of anxiety and neuroticism (rs391957, HSPA5) were found to have higher frequency in LLIs." (PMID 39567526, 2024). "Therefore, the gene encoding estrogen receptor 1, one of two mediators of estrogen action, has been considered as an important candidate for the determination of osteoporosis risk." (PMID 30241506, 2018). "The expression pattern of IL17RC, COL1A1, and ESR1 can be useful in osteoporosis detection, which may help in identifying those populations at high risk for osteoporosis, and in directing treatment of osteoporosis." (PMID 23731710, 2013). "A significant gene-gene interaction between ESR1 (rs2228480) and RANK (rs3018362) increased osteoporosis risk (OR = 2.1 [1.4-3.2], CVC = 10/10), and a gene-gene model involving ESR1, IL6R, IL1β, and RANKL was identified for hip fracture (CVC = 8/10)." (PMID 41929826, 2026). "Previous studies have found that ESR1 is a key target in regulating osteoclast differentiation and osteoporosis." (PMID 41019997, 2025). "As previous studies have shown that ESR1 is a key target in the regulation of osteoclast differentiation and osteoporosis." (PMID 41019997, 2025). "In the findings of this study, qRT-PCR validation conducted on patients with sarcopenia and osteoporosis revealed a reduction in the expression of the ESR1 and NRP2 genes in both bone and muscle tissues." (PMID 40660573, 2025).